TNF (tumor necrosis factor)
Diseases named in the same sentence as TNF in open-access papers (continued):
Sharing a sentence is not in itself a finding about the gene and the disease.
HIV-1 infection (123 papers, 1992 to 2026). The type species of lentivirus and the etiologic agent of acquired immunodeficiency syndrome (AIDS). "HIV-1 infection is also associated with persistent elevated TNF, a known activator of miR-155 expression in endothelial cells and in synoviocytes, which is consistent with our PBMC results." (PMID 36766808, 2023). "HIV-1 infection was associated with significantly lower production of IL-2, TNF-α and IFN-γ in response to T. gondii from early/asymptomatic stages, when comparing P2 patients to C2 controls." (PMID 37224128, 2023). "Although viral products are known to be associated with neuronal damage, the major cause of neurotoxicity observed with HIV-1 infection is through the innate immune system, induced by the release of proinflammatory cytokines such as TNF-α and IL-1β." (PMID 37631062, 2023). "Other recent work also suggests that HIV-1 infection in primary human microglia cells causes the release of IL-6, IL-8, TNF-α, CCL2, and regulated-upon-activation, normal T cell-expressed and -secreted (RANTES) proteins." (PMID 34440127, 2021). "Five biomarkers (ITAC, IL-8, IL-7, TNFα, and Fractalkine) were identified as the most significant contributors to the signature associated with future HIV-1 infection." (PMID 33731158, 2021). "A hallmark of HIV-1 infection is immune activation and inflammation with increased levels of TNF in the plasma and the tissues." (PMID 28358311, 2017). "Both IFN-γ and TNF-α are important mediators of antiviral activity by CD8+ T cells in HIV-1 infection whilst increased production of IL-2 is associated with reduced viral loads in elite controllers." (PMID 27427967, 2016). "The TH1 cytokine TNF-α was significantly up-regulated in HCs at baseline, while HIV-1 infection caused a reduction in secreted TNF-α comparable to infected-MDMs." (PMID 23217137, 2012). "In clinic, TNFα has also been implicated in the pathogenesis of HIV-1 infection, promoting HIV replication in T cell lines and in lymphocytes in HIV-infected patients." (PMID 21599974, 2011). "In addition, HIV-1 infection was associated with poor IFNγ and TNF production by MAIT cells following E. coli stimulation despite long-term cART in line with previous observations." (PMID 36341446, 2022). "However, TNF-α has been linked to the immune activation and the enhancement of HIV-1 infection in CD4+ T cells." (PMID 24156302, 2013). "In our cohort of Caucasian Spaniards, TNF-α genetic variants could be involved in the vulnerability to HIV-1 infection." (PMID 20420684, 2010). "In summary, in a cohort of Caucasian Spaniards, polymorphism within the TNF-α gene may be associated with vulnerability to HIV-1 infection." (PMID 20420684, 2010). "In this cohort of Caucasian Spaniards, we found that TNF-α gene polymorphism may be involved in vulnerability to HIV-1 infection." (PMID 20420684, 2010). "We aimed to determine whether carriage of the TNF-α-238G>A, -308G>A and -863 C>A gene promoter single nucleotide polymorphisms (SNP) and the CCR5Δ32 variant allele influence the risk of HIV-1 infection and disease progression in Caucasian Spaniards." (PMID 20420684, 2010). "Our data indicate that none of the individual polymorphisms assessed influence vulnerability to HIV-1 infection, but haplotype analyses suggest that the combination of some genetic variants within the TNF-α gene may modulate the risk of infection." (PMID 20420684, 2010). "Similar to what is observed during aging, HIV-1 infection can generate an inflammatory environment by causing the release of viral proteins (such as Tat and gp120) and cellular products (such as proinflammatory cytokines, e.g., TNF-α, IL-8, IL-6, and IL-1β) from cells." (PMID 31614895, 2019). "Here, we performed RNA sequencing of polyadenylated transcripts from a human microglial cell line exposed to HIV-1 infection or TNF-α stimulation to investigate transcriptional responses and identify lncRNAs with potential regulatory functions." (PMID 41977450, 2026).
HIV-1 infection (continued). "Tnfrsf1b from R. norvegicus is involved in six distinct pathways such as “TNF signaling”, “cytokine–cytokine receptor interaction”, “HIV-1 infection”, and “ALS”." (PMID 40869347, 2025). "Increased cytokine production by NK cells, specifically TNF and IFN-γ, have been associated with protection against HIV-1 infection in HESN IDUs." (PMID 39459918, 2024). "Like IL-6, Tumor Necrosis Factor (TNF) is a pro-inflammatory cytokine that is elevated in HIV-1 infection and contributes to pathology." (PMID 39205287, 2024). "In HIV-1 infection, TNF-α secretion by multiple infected cells, including activated macrophages and T cells, is induced by HIV viral proteins Tat and gp120 released extracellularly." (PMID 38675885, 2024). "The mechanism by which HIV-1 infection upregulates TNFα production involves HIV-1 accessory proteins, Nef, Vpr, and Tat, which activate the nuclear factor-kB signaling." (PMID 38280430, 2024). "At the protein level, we observed these M1 inflammatory factors (TNF-α, IL-1β, and IL-6) sustained the release to the supernatant during HIV-1 infection." (PMID 37798121, 2023). "Under the condition of glycolysis inhibition, we observed that the expression of M1 markers TNF-α, IL-1β, and IL-6 was also reversed, indicating that blocking glycolysis inhibits M1 polarization of macrophages driven by HIV-1 infection." (PMID 37798121, 2023). "In HIV-1 infection, TNF-α mediates the apoptosis of HIV-infected cells and suppresses HIV-1 replication in the freshly infected peripheral blood monocytes." (PMID 37376629, 2023). "We identified a cluster of IRPs (cluster 7), including CXCL11, CXCL9, TNF, CXCL10, and IL18, which was closely associated with T cell dysregulation during chronic HIV-1 infection." (PMID 36408648, 2023). "Elevated proinflammatory cytokines, such as TNF-α, IL-6, and IL-1β, appeared in the plasma and lymph nodes from the early stage of HIV-1 infection." (PMID 38138916, 2023). "We also found a high systemic burst of several plasma cytokines (IFN-γ, TNF-α, IP-10, and IL-18) in agreement with the charateristic cytokine storm of acute HIV-1 infection in humans." (PMID 36800238, 2023). "Double-positive IFN-γ/TNF-α and polyfunctional CD8 T cell responses associated with an enhanced control of HIV-1 infection were increased following combination treatment." (PMID 35865519, 2022). "TNF-α is involved in the pathogenesis of HIV-1 infection, and serum concentrations of TNF-a have been shown to increase with the progression of HIV-1." (PMID 35990692, 2022). "Elevated amounts of TNFα have been detected in plasma and tissues at all stages of HIV-1 infection, even in patients on ART and undetectable viral load." (PMID 35372109, 2022). "Future work will investigate the mechanism by which C. neoformans represses TNF-α expression induced by HIV-1 infection both through regulation of NF-κB activation and potential posttranscriptional regulation of the TNF-α mRNA." (PMID 33762317, 2021). "Recent findings suggest that HIV-1 infection can produce an inflammatory environment due to the induction of viral proteins (such as Tat and gp120) and proinflammatory cytokines (e.g., TNF-α, IL-8, IL-6, and IL-1β)." (PMID 34440127, 2021). "Nonetheless, C5a increases TNF-α and IL-6 release, thereby promoting HIV-1 infection, whilst inhibition of its receptor C5aR reverses this action." (PMID 34502066, 2021). "On the other hand, these cells have been confirmed to have a role in chronic HIV-1 infection, where they were found to be expanded and responsible for the overproduction of TNF-α and Il-β, which was confirmed in the current study." (PMID 34578386, 2021). "CD14+CD16+ cells were described as a subset of monocytes that is more susceptible to HIV-1 infection than CD16− cells, and they are an important source of the pro-inflammatory cytokine tumor necrosis factor (TNF)." (PMID 32849508, 2020).
HIV-1 infection (continued). "HIV-1 infection of macrophages and microglia in the CNS leads to cellular activation and secretion of neurotoxic cytokines such as IL-1β and TNF-α." (PMID 33171974, 2020). "Apart from the intrinsic upregulation of NF-κB transcription during HIV-1 infection, macrophage-derived inflammatory cytokines, IL-1β and TNF-α, are known to activate NF-κB signaling and induce a reactive astrogliosis phenotype in astrocytes." (PMID 33171974, 2020). "The capacity of CD161+ CD4+ T cells to produce IFNγ, TNF, and IL-17 was decreased post-HIV-1 infection compared to pre-infection." (PMID 33322496, 2020). "Another study showed that HIV-1 infection in primary human microglia induced the secretion of IL-6, IL-8, TNF-α, C-C Motif Chemokine Ligand 2 (CCL2), and Regulated upon Activation, Normal T cell Expressed and Secreted protein (RANTES)." (PMID 31614895, 2019). "TNF-α mimics the effect of HIV-1 infection, which activates the NF-kB transcription factor and leads to the production of TNF-α." (PMID 29951068, 2018). "Among them, impaired production of IFN-α and TNF-α regulated in pDCs by TIM-3 can play an important role in the immunopathogenesis of HIV-1 infection." (PMID 29597250, 2018). "Both immune activation and viral reservoirs are hallmarks of HIV-1 infection and involve the TNF/TNFR pathway." (PMID 28358311, 2017). "Of interest, TNF-α stimulation counteracted the downregulation of MHC-I molecules induced by HIV-1 infection in PM1-IIIB cells." (PMID 28051183, 2017). "At all stages of HIV-1 infection, increased amounts of TNF can be detected either in the plasma or in the tissues." (PMID 28358311, 2017). "In accordance to that, TNFα inhibitors are able to impair HIV-1 replication, and anti-TNFα treatments have been proposed to combat HIV-1 infection in combination with other therapies." (PMID 27351838, 2016). "It was initially cloned from human fetal astrocytes following HIV-1 infection or tumor necrosis factor-alpha treatment." (PMID 27765924, 2016). "During chronic HIV-1 infection there was an increase of IL-10, TNF- α, IL-2, IL-6, IL-13 and IL-22 levels when compared to the control group." (PMID 27356504, 2016). "Concentrations of IL-10, IL-4 and TNF-α were increased in the acute HIV-1 infection when compared to the control group." (PMID 27356504, 2016). "The expression of TNF-α and TNFR increases during HIV-1 infection and is associated with the depletion of T cells." (PMID 25835530, 2015). "Following HIV-1 infection activated macrophages release TNF-α as a soluble factor or expressed as a membrane-bound form that binds to TNFR2." (PMID 25835530, 2015). "HIV-1 infection can elicit an innate immune response, resulting in the production of interferons (IFNs) or pro-inflammatory cytokines such as TNF-α." (PMID 26297639, 2015). "HIV-1 infection of macrophages activates host transcription factors such as NF-kB and prevents the macrophages from TNF-induced apoptosis." (PMID 25835530, 2015). "TNF-α homeostasis is profoundly altered by HIV-1 infection itself and it has been shown that HIV-1 infected patients have elevated pre-treatment levels of TNF-α but these levels dramatically decrease when cART is initiated." (PMID 24958357, 2014). "In this report, we found that TNF-α induced during HIV-1 infection play a key role in HIV-1-induced necroptosis." (PMID 24714696, 2014). "Increase in proinflammatory cytokines like IL-1β, IL-6 and tumor necrosis factor (TNF)-α follows soon after initial HIV-1 infection." (PMID 24662979, 2014). "We also confirmed that TNF-α is significantly increased during HIV-1 infection in primary CD4+ T-lymphocytes." (PMID 24714696, 2014). "It has been reported that TNF-α system was activated during HIV-1 infection and the raised levels increased with disease progression and degree of immunodeficiency." (PMID 24358317, 2013). "HIV-1 infection induces TNF expression, and high amount of TNF is present in all stages of HIV-1 infection." (PMID 24453421, 2013).
HIV-1 infection (continued). "We have shown that HIV-1 infection in macrophages or treatment of astrocytes with TNF-α and HIV-1 modulates CXCL10 expression, which leads to neuro-toxicity." (PMID 23078780, 2012). "For example, HIV-1 infection of monocyte-derived macrophages (MDMs) in vitro generally inhibits phagocytosis and elicits a cytokine response leading to secretion of tumor necrosis factor-alpha (TNF-α), interleukin-1 (IL-1), IL-6 and IL-8, among others." (PMID 22412921, 2012). "Milk from two of these subjects contained high levels of multiple pro-inflammatory cytokines including TNFα, IL-1β, IL-6, IL-8, MIP-1α, MIP-1β, MCP-1 and IP-10, and enhanced cell-associated HIV-1 infection at dilutions as high as 1∶500." (PMID 22952771, 2012). "During HIV-1 infection in the brain, proinflammatory cytokines such as IL-1β and tumor necrosis factor (TNF)-α are released by infiltrating HIV-1 infected macrophages." (PMID 23029125, 2012). "On further in vitro investigation of astrocytes, macrophages, and lymphocytes, we found that CXCL10 was induced by HIV-1 infection or treatment with TNF-α or IFN-γ, suggesting that myeloid and lymphoid cell populations are key players in CXCL10." (PMID 23078780, 2012). "The immuno-regulatory response of the host influences the pathogenesis of HIV-1 infection, triggering monocytes, macrophages, and natural killer cells to produce TNF-α." (PMID 22164280, 2011). "We used a novel model of HIV-1 infection to study proviral latency in actively dividing T cells, of which the majority only support viral gene expression after TNFα activation." (PMID 21923919, 2011). "In both case, the result is a high level of pro-inflammatory cytokines, such as tumor necrosis factor alpha, interleukin 6 and interleukin 1 beta, right from the early stages of HIV-1 infection." (PMID 21362195, 2011). "Previous reports have demonstrated the usefulness of TNF-α inhibition by CC-3052 treatment, both in acute and chronic HIV-1 infection in vitro." (PMID 21949656, 2011). "TNF-α and CCR5Δ32 genotype and allele frequencies in HC, EU and HIV-1-infected for assessment of associations with the risk of HIV-1 infection." (PMID 20420684, 2010). "Investigations suggest that TNF-α is involved in the pathogenesis of HIV-1 infection since it is overproduced by infected individuals." (PMID 20420684, 2010). "Tumor necrosis factor alpha (TNF-α) is thought to be involved in the various immunogenetic events that influence HIV-1 infection." (PMID 20420684, 2010). "High levels of proinflammatory cytokines, such as tumor necrosis factor α (TNFα), interleukin (IL)-1β and IL-6 in both plasma and lymph nodes are observed from the early stages of HIV-1 infection." (PMID 20380696, 2010). "In this study we have assessed the influence of TNF-α SNP on the vulnerability to HIV-1 infection and, in infected patients, on disease progression." (PMID 20420684, 2010). "Little data is available on the influence of TNF-α SNP on these uncommon clinical forms of HIV-1 infection." (PMID 20420684, 2010). "Several cohort studies have assessed the influence of TNF-α SNP on the immunogenetics of HIV-1 infection." (PMID 20420684, 2010). "This implies that TNF-α would increase viral replication in the placenta when the initial resistance to cell-free HIV-1 infection in vivo is bypassed, after cell-to-cell infection for example." (PMID 16796744, 2006). "This implies that in vivo TNF-α would increase viral replication in the placenta when the initial resistance to cell-free HIV-1 infection is bypassed, after cell-to-cell infection for example." (PMID 16796744, 2006). "Because blood–brain barrier damage and impaired cerebral perfusion are common features of HIV-1 infection, we evaluated the role of tumour necrosis factor-α (TNF-α) and interleukin-1β (IL-1β) in mediating disruption of the blood–brain barrier." (PMID 18475460, 1992).
HIV-1 infection (continued). "We have recently reported that tumour necrosis factor-α (TNF-α) mediates active neural inflammation and blood-brain barrier damage in HIV-1 infection." (PMID 18475479, 1992). "However, in the context of HIV-1 infection, TNF-α enhances HIV-1 Tat-induced neurotoxicity by oxidative stress leading to neuronal apoptosis." (PMID 40313367, 2025). "In this study, we infected Jurkat cells with pseudotyped virus HIV-1NL4-3-ΔEnv-GFP-Bcl2 to obtain a latent HIV-1 infection model that is more sensitive to R5M4 than to TNF-α (TNF-α is used as a reactivator in the construction of several HIV-1 latent infection cell models)." (PMID 39692477, 2025). "HIV-1 infection, whether its Gag was WT or ΔMA, increased the expression of TNFα to similar levels, suggesting that HIV-1 elements other than Gag was responsible for the upregulation of TNFα expression." (PMID 38280430, 2024). "In the control cells, TNFα secretion was enhanced upon HIV-1 infection." (PMID 38280430, 2024). "HIV-1 infection is accompanied by dysregulation of cytokine production in vivo and in vitro, with downregulation of interleukin (IL)-2 and interferons and upregulation of proinflammatory cytokines IL-1, IL-4, IL-6, IL-10, and TNFα." (PMID 38280430, 2024). "HIV-1 infection increased TNFα secretion in Jurkat, U937, and THP-1 cells." (PMID 38280430, 2024). "The cotransport of TNFα and Gag via Syx6-mediated vesicles may partly explain the upregulation of TNFα upon HIV-1 infection." (PMID 38280430, 2024). "Disease progression, however, positively correlates with higher TNF levels in chronic phase HIV-1 infection, plausibly as a consequence of TNF modulation by HIV-1 proteins to enhance viral replication, suggesting a deleterious effect in the later stages of infection." (PMID 39459918, 2024). "Here, substantial increases in TNFα, IL-8, and IL-1β were observed after HIV-1 infection." (PMID 35132117, 2022). "We found that on days 3 and 5 post-HIV-1 infection, TNF-α expression increased more than 100-fold." (PMID 33762317, 2021). "Given that (i) HIV-1 infection of macrophages induces proinflammatory tumor necrosis factor alpha (TNF-α) production and (ii) C. neoformans exhibits anti-inflammatory effects (reviewed in reference 5), we set out to investigate the impact of coinfection on the inflammatory activation of macrophages." (PMID 33762317, 2021). "Other mechanisms that may contribute to ongoing platelet activation in HIV-1 infection could include production of TNF, which activates platelets; and of platelet-activating factor (PAF), the bioactivity of which is increased in HIV-1 infection." (PMID 33329587, 2020). "cAMP signaling is known to be increased during HIV-1 infection or by TNFα stimulation." (PMID 32746944, 2020). "Furthermore, we also found that the HIV-1 infection-augmented tumor necrosis factor-alpha (TNF-α) plays a key role in inducing necroptosis and HIV-1 Envelope and Tat proteins function as its co-factors." (PMID 24714696, 2014). "As TNF-α plays an important role during necroptosis and its generation from T-lymphocytes significantly increased during HIV-1 infection, we sought to determine whether the TNF-α is also a key factor for HIV-1-induced necroptosis." (PMID 24714696, 2014). "We further investigated whether HIV-1 infection (M-tropic) in macrophages or treatment of astrocytes with TNF-α and HIV-1 (T-tropic or M-tropic) provoked the same proinflammatory response as that in patients." (PMID 23078780, 2012). "HIV-1 infection had variable effects on TNF mRNA levels in response to IE-PPS phagocytic targets." (PMID 22363802, 2012). "We also have reported that cytomegalovirus blocks stromal inhibition of HIV-1 infection of macrophages and that this inhibition is mediated, at least in part, by cytomegalovirus-induced monocyte production of TNF-α, which acts in trans to enhance HIV-1 replication." (PMID 21637819, 2011).